TNF (tumor necrosis factor)
Diseases named in the same sentence as TNF in open-access papers (continued):
Sharing a sentence is not in itself a finding about the gene and the disease.
food allergy (continued). "Lack of IL-4 has been recently reported to modulate gut mucosal response in food allergy through diminished expression of TNF-α mRNA, increased Th1 IFN-γ, IL-12p40 regulatory cytokines, thus demonstrating their relevance in the control of allergic inflammatory processes, especially in the intestine." (PMID 20184725, 2010). "In addition, studies have indicated that the upregulation of TGF-β and the inhibitory effect of TNF-α at the intestine of food allergy animals may prevent an impaired intestinal barrier function." (PMID 36499554, 2022). "In food allergies, bile acids inhibit NF-κB activation by activating FXR, thereby reducing the production of pro-inflammatory cytokines such as TNF-α, IL-6, and IL-1β." (PMID 40735411, 2025). "Notably, pathways such as TNF signaling, vitamin D biosynthesis, lactate dehydrogenase activity, and necroptotic signaling were enriched, indicating that both immune regulation and metabolic mechanisms play crucial epigenetic roles in food allergy pathogenesis." (PMID 41153772, 2025). "In cord blood, infants who developed food allergies showed a higher ratio of monocyte/CD4+ T cells, which would secrete higher amounts of inflammatory cytokines, such as IL-1β, IL-6, and TNF-α that further suppressed IL-2 expression by CD4+ T cells." (PMID 38263182, 2024). "A study demonstrated that only the level of TNF-α was increasing in the cerebral cortex of food allergy mice; the levels of IL-1β and IL-6 were not changed." (PMID 40429903, 2025). "The results showed that the antigen-specific IgE, but not IgG4, IL-4, IFN-γ, IL-17 and TNF-α were detected in all the IBD patients with food allergy." (PMID 27499766, 2016). "Our data show that the serum levels of IgE and TNF-α were suppressed in the patients with IBD and food allergy after the treatment with SIT and CB, indicating that the therapy also blocked mast cell activation since mast cells are one of the major sources of TNF-α in the body." (PMID 27499766, 2016). "However, with the exception of TNFα, which was lower, none of the other NK cell markers in our panels differed in children with food allergy." (PMID 28767726, 2017). "Among all the markers and functions evaluated, only TNFα was significantly lower in children with food allergy compared to those without food allergy and those with unknown status." (PMID 28767726, 2017). "TNF alpha together with faecal calprotectin, alpha 1 antitrypsin beta defensin, EDN, and CP have been proposed as biomarkers of non-IgE-mediated food allergy." (PMID 39085570, 2024).
head and neck cancer (33 papers, 2014 to 2025). A primary or metastatic malignant neoplasm affecting the head and neck. "A study of the plasma from head and neck cancer cachectic patients showed the downregulation of plasmatic miR-130a expression correlated to a higher plasma concentration of tumor necrosis factor-alpha (TNF-α) and risk of being classified as cachectic." (PMID 35892590, 2022). "A previous study that detected salivary cytokines in patients with head and neck cancer with concurrent CTx and RT reported a significant increase in the salivary levels of IL-1β, IL-6, and TNF, that were all positively associated with the mucosal toxicity severity." (PMID 35476641, 2022). "Additionally, consumption of curcumin reduced activity of IKKb in a study of patients with head and neck cancer and this was associated with a decrease in the expression of IL-8, TNF-α, and IFN-g." (PMID 33206688, 2020). "The head and neck cancer patients’ salivary cytokines that were assessed by the studies, along with photobiomodulation therapy, included IL-12p70, TNF-α, IL-6, IL-8, IL-10, CXCL8, and IL-1β." (PMID 38792366, 2024). "Collectively, these results show that Ad5/3-E2F-D24-hTNFa-IRES-hIL-2 is capable of replicating in and lysing several types of human head and neck cancer, with subsequent release of TNFα and IL-2, despite histology or tumor location." (PMID 35355980, 2022). "The outliers of IL-6, IL-10 and TNF in the post-index group were detected in saliva samples from different patients with head and neck carcinoma, and all sampling time was at OM occurrence." (PMID 35476641, 2022). "We studied the TNFα/TNFR1 signaling pathway using a 4-NQO-induced model of head and neck cancer utilizing immunocompetent C57BL/6 mice." (PMID 34650923, 2021). "Actually, another dual antagonist of cIAP/XIAP, ASTX660, was reported to sensitize head and neck cancer to tumor necrosis factor (TNF) family death ligands (such as TNF and TRAIL) and radiation." (PMID 32188144, 2020). "In a recent study on a cohort of 32 patients with head and neck cancer treated with chemoradiotherapy IL-1β and TNF-α levels decreased 60 days after treatment as compared to the pre-treatment level whereas IL-6 levels increased." (PMID 31750257, 2019). "The enhanced expression of IL-1β after GW5074 treatment was related to an increased phosphorylation of MEK1 and ERK1/2, indirectly confirming that activation of EGFR-downstream MEK and ERK affect IFNγ/TNFα induced chemokine secretion in head and neck cancer." (PMID 30192802, 2018). "Identifying more specific genotypic expression of TNF-α from serum samples of head and neck cancer patients may also provide another avenue to guide prognosis." (PMID 36980727, 2023). "A retrospective cohort study in the USA showed that patients treated with tumor necrosis factor inhibitor did not have a significantly increased risk of head and neck cancer recurrence." (PMID 36514134, 2022). "In a study by that longitudinally evaluated the saliva of patients with head and neck cancer undergoing treatment with RT and CRT, was showed an increase in cytokines IL-1β, IL-6 and TNFα in the saliva of patients who underwent CRT compared to RT." (PMID 38725825, 2024). "TNF-α is another important biomarker being investigated in OSCC and head and neck cancers in general." (PMID 36980727, 2023). "The head and neck carcinoma group had significantly higher concentrations of IL-8, TNF, and VEGF in the pre-index group, and IL-1β and TNF in the post-index group." (PMID 35476641, 2022). "Indeed, the other researchers had assessed the presence of salivary cytokines (e.g., IFN-γ, IL-1β, IL-6, IL-8, IL-10, TNF-α, VEGF) in patients with head and neck cancer (HNC)." (PMID 29515773, 2018).
hyperandrogenism (33 papers, 2014 to 2025). Excessive secretion of androgens from the adrenal glands or gonads. "PCOS and hyperandrogenism in women have been linked to certain polymorphisms of TNF-α and its type 2 receptor, and individuals with PCOS have overexpressed TNFR2." (PMID 39202691, 2024). "Inflammation was linked with hyperandrogenism since proinflammatory cytokines (e.g., TNF-α) stimulated the proliferation of androgen-producing theca cells." (PMID 36662487, 2022). "Increased TNF-α can promote insulin resistance and cause hyperandrogenism." (PMID 39202691, 2024). "Moreover, high TNF-α level has recently been linked to the development of IR and hyperandrogenism." (PMID 36661246, 2023). "Compared to IL-6 and TNF-α, IL-1β has a more localised impact on ovarian dysfunction and hyperandrogenism." (PMID 40385768, 2025). "These immune cells release inflammatory cytokines, such as tumor necrosis factor-alpha (TNF-α), interleukin-6 (IL-6), and interleukin-1β (IL-1β), which impair insulin signaling and exacerbate androgen excess." (PMID 41382225, 2025). "A large body of evidence has shown that hyperandrogenism in PCOS patients is closely related to inflammation-related genes such as TNF-α, Tnf receptor 2 (TNFR2) and IL-6." (PMID 39453929, 2024). "CpG hypomethylation in genes such as AKR1C3, GHRHR, MAMLD1 and RETN, and hypermethylation in TNF, which can indirectly contribute to androgen excess, were consistent with increased and decreased levels of the respective gene transcripts." (PMID 30975191, 2019). "There is a positive relationship between hyperandrogenism and serum TNF-α excessive concentration as hallmarks in patients with PCOS." (PMID 24693338, 2014). "TNF-α can trigger hyperandrogenism and CRP is along with low-grade inflammation." (PMID 38778429, 2024). "This in vitro study was designed to evaluate the effect of TNF-α on GCs with hyperandrogenism." (PMID 37427330, 2023). "Recent research has shown that CpG hypomethylation regarding GHRHR, AKR1C3, RETN, and MAMLD1 and hypermethylation regarding TNF, which can indirectly contribute to androgen excess, were consistent with increased and decreased levels of the corresponding gene transcripts, respectively." (PMID 33763111, 2021). "ROS also stimulate the production of inflammatory markers such as tumor necrosis factor alpha (TNF-α) and nuclear factor kappa-light-chain-enhancer of activated B cells, both of which cause an increase in androgen production and reinforce the development of symptoms caused by hyperandrogenism." (PMID 36768170, 2023). "The current study observed a notably upregulated expression of TNF-α, IL-6 as well as NF-κB in the PCOS group, which was accompanied with metabolic disturbances and hyperandrogenism." (PMID 38589892, 2024). "Other mechanisms have also been proposed including increased levels of pro-inflammatory proteins, tumor necrosis factor (TNF), and hyperandrogenism." (PMID 36429632, 2022). "A meta-analysis showed that TNF levels in women with PCOS were significantly higher compared to healthy controls and that high serum TNF concentration was related to IR and androgen excess but not to the body mass index (BMI)." (PMID 33138337, 2020). "When women with PCOS were divided into those with and without hyperandrogenism, the TNF-α serum level was significantly higher among women with PCOS compared with controls, as well as in the hyperandrogenism group compared with those without hyperandrogenism." (PMID 30134857, 2018).
pneumococcal infection (33 papers, 2006 to 2025). Infections with bacteria of the species streptococcus pneumoniae. "For instance, TREM2-deficient alveolar macrophages (AMs) produce less TNF-α and cytokine-induced neutrophil chemoattractant after Streptococcus pneumoniae infection." (PMID 39405126, 2024). "Mice deficient in TNFα and IL-1 receptors (IL-1R) were shown to be more susceptible to pneumococcal infection and had a high bacterial load in the lungs." (PMID 36816580, 2023). "The pneumococcal infection was also associated with a significant increase in the expression of IL-6, TNF-α, CXCL1, and IFNγ in both groups and was significantly higher in the Zip8KO group when compared to the WT animals (p = 0.055)." (PMID 35162945, 2022). "Increased levels of TNF-α and IL-6 during pneumococcal infection are associated with severity of disease." (PMID 32318074, 2020). "Decrease in the ability of susceptible (CBA/Ca) mice to induce rapid TNF activity following pneumococcal infection, for example, increases the susceptibility of these mice to infection, when compared with the resistant (BALB/c) strain." (PMID 26934748, 2016). "Pneumococcal infection can enhance the concentrations of TNF, IL-1β, IL-6, IFN-γ, and IL-10 in the respiratory tract and blood of immunocompetent well-nourished mice, while in protein-malnourished the levels of those immune mediators are significantly lower." (PMID 40507039, 2025). "These IL-1β and TNFα play a major role in stimulating NF- kβ activation in the pulmonary epithelium and have been observed in most cases of pneumococcal infection." (PMID 38234660, 2024). "Tumor Necrosis Factor alpha (TNFα) and Iinterleukin-1 (IL-1) signaling is critical for the activation of robust inflammatory responses and recruitment of neutrophils during pneumococcal infection of the airway." (PMID 36816580, 2023). "Pneumococcal infection of air-liquid interface cultures increases the production of inflammatory cytokines IL-1β and TNF." (PMID 35044807, 2022). "Specific depletion of these monocytes or reduction in TNF levels enhanced immunity to pneumococcal infection and increased clearance in old mice." (PMID 34113578, 2021). "In our study however, both TNF-α and IL-1β were upregulated in the lungs of gut microbiota-disrupted mice compared to the undisrupted controls after pneumococcal infection." (PMID 30562386, 2018). "IL-10 modulates pulmonary inflammation that occurs in the context of pneumococcal infection by constraining the expression of TNF-α, IFN-γ, and IL-6." (PMID 29990318, 2018). "The massive production of cytokines such as TNF-α, IL-6, IL-12, CXCL1, and CXCL2 was a hallmark of the secondary pneumococcal infection after the flu." (PMID 29326698, 2017). "Pneumococcal infections also determined higher levels of TNF-α in blood of old patients when compared to those of young patients." (PMID 16571118, 2006). "Also, the analysis of tumor necrosis factor (TNF)-alpha would extend the analysis of Trm cells especially with regard to limiting invasive pneumococcal infections." (PMID 33595670, 2021). "Given the important role of TNF-α in the inflammatory response, the present study provides new insight into the mechanisms that govern production of inflammatory mediators in macrophages during pneumococcal infection." (PMID 18796140, 2008). "Production of TNF-α may contribute significantly to the inflammatory response raised during pneumococcal infection." (PMID 18796140, 2008). "Interestingly TLR2/CD14 KO mice produced less TNF than wt mice, which indicates that besides TLR2 as the major regulator, CD14 participates in a temporally and locally coordinated action in controlling TNF during pneumococcal infection." (PMID 17428319, 2007).
pneumococcal infection (continued). "However, pneumococcal infection-induced proinflammatory cytokines, including tumor necrosis factor α (TNFα), interleukin (IL)-6, and IL-1β, are largely intact in the STING−/− mice, and the bacterial burden in the lung, spleen, and blood were comparable between STING−/− and wild-type (WT) mice." (PMID 34512626, 2021). "However, TNF-α production was significantly reduced in the lungs of dually infected mice compared with S. pneumoniae-infected mice when bacterial loads were similar between the two groups after pneumococcal infection at 7 dpi in our study." (PMID 33722928, 2021). "In the present study, the TLR4-deficient mice had lower TNF-α and IL-1β levels and decreased pulmonary resistance after S. pneumoniae infection compared to wild-type mice, indicating that the TLR4 pathway mediates the immune response against pneumococcal infection." (PMID 30562386, 2018). "Interestingly, we found that the levels of NF-κB-related cytokines including TNF-α and IL-6 in the culture media were significantly increased in the early stage of pneumococcal infection, whereas cytokine levels were generally maintained during a 4-8 h infection or reduced at 8 h after infection." (PMID 26683708, 2015). "The results showed that by 24 h after pneumococcal infection there was a significant increase of protein production of CXCL1, IL-6, TNF-α, CXCL10 and G-CSF in virus/S." (PMID 24408967, 2014). "In addition, both immunomodulatory CRL431 and CRL1505 strains improved the production of TNF, IL-1β, IL-6, and IFN-γ in the respiratory tract compared to malnourished and BCD-treated mice, after the pneumococcal infection." (PMID 40507039, 2025). "utilized FMT in a mouse model of gut microbiota depletion and demonstrated that lung bacterial counts, as well as levels of tumor necrosis factor-α (TNF-α) and interleukin-10 (IL-10), returned to normal levels in FMT-colonized mice within six hours following pneumococcal infection." (PMID 40861492, 2025). "At day 7 post-pneumococcal infection, circulating TNFα and IL-1β were not significantly different across the groups." (PMID 29980196, 2018). "Studies have shown that piliated S. pneumoniae induce higher tumor necrosis factor (TNF) responses than the non-piliated during pneumococcal infection." (PMID 29988379, 2018). "In addition, the production of IL-10, IL-6, and TNF-α did not significantly change, notably in contrast to IL-1β, which was significantly enhanced after pneumococcal infection at 14 dpi in our study." (PMID 33722928, 2021).